KRAS (KRas proto-oncogene, GTPase)
Diseases named in the same sentence as KRAS in open-access papers (continued):
Sharing a sentence is not in itself a finding about the gene and the disease.
rectal cancer (continued). "Mutually exclusive KRAS and NRAS mutations were identified, with recurrent activating mutations observed commonly in colon and rectal carcinoma (COAD/READ) (30%, 5%, and 5% for KRAS (Gly 12), KRAS (Gly 13), and NRAS (Gln 61), respectively)." (PMID 38920700, 2024). "TNM stage and molecular markers (MMR, BRAFV600E, and KRAS), BMI, and family history were similar between patients with early-onset rectal cancer and patients with average-onset rectal cancer." (PMID 37462969, 2023). "KRAS mutation status is a predictor of poor response to anti-EGFR antibody therapy in metastatic CRC, and its correlation with rectal cancer response to CRT has been widely studied although a consensus was not reached." (PMID 35860583, 2022). "While more work is clearly needed to better understand how this contributes to the malignant potential of KRAS‐mt rectal cancer, our analyses constitute a step forward in the characterization of the dysregulated biological processes orchestrated by KRAS." (PMID 33817986, 2021). "A number of studies suggest that glucose accumulation in PET/CT is significantly associated with genetic mutations (KRAS, KRAS/BRAF, or KRAS/NRAS) in primary CRC, metastatic CRC, or rectal cancer." (PMID 34239564, 2021). "Locally advanced rectal cancer (LARC) is a heterogeneous disease with little information about KRAS status and image features." (PMID 34026605, 2021). "In rectal cancer patients, KRAS mutant (KRAS-mut) patients have a worse prognosis, which emphasizes the importance of detecting KRAS status for prognostic evaluation and treatment strategy selection." (PMID 34026605, 2021). "Overall, our preliminary results demonstrate that MRI features, including quantitative texture analysis derived from T2 weighted images, have the potential to differentiate the KRAS status in rectal cancers." (PMID 31727020, 2019). "Hence, the main objects of the present study were to 1) retrospectively analyze the differences of radiologic features in rectal cancer with different KRAS status; 2) investigate whether texture features extracted from T2 weighted image scan differentiate KRAS mutation status in rectal cancers." (PMID 31727020, 2019). "The MRI findings of rectal cancer, especially texture features, showed an encouraging value for identifying KRAS status." (PMID 31727020, 2019). "Mean values of six texture features were significantly different in rectal cancers with different KRAS status (p < 0.0001)." (PMID 31727020, 2019). "A 68-year-old man was first diagnosed with metastatic KRAS wild-type rectal cancer at the age of 65 and was treated with FOLFOX plus bevacizumab for 5 months and upon progression was treated with FOLFIRI plus cetuximab for a subsequent 8 months." (PMID 30923702, 2019). "A 42-year-old man was diagnosed with KRAS wild-type and BRAF D594N mutated stage III rectal carcinoma." (PMID 30923702, 2019).
rectal cancer (continued). "One patient was a 51-year-old female with KRAS amplified rectal cancer with synchronous diffuse metastases (lung and liver)." (PMID 28178681, 2017). "The mutational profiles (KRAS, MMR, CIMP) of LSCC and rectal cancer were similar, but were different from that of RSCC." (PMID 28801584, 2017). "By adding the herein largest patient cohort and analyzing the KRAS status in different pre-therapeutic biopsies from the same tumor we can add additional confidence to the clinical practice of KRAS testing in rectal cancer." (PMID 27064574, 2016). "We evaluated the tumor response and survival according to the KRAS oncogene status in locally advanced rectal cancer." (PMID 26252300, 2015). "Frequencies of tumor KRAS, BRAF, and PIK3CA point mutations and ERBB2 amplification in 63 patients with locally advanced rectal cancer." (PMID 23226389, 2012). "Point mutations in KRAS, BRAF, and PIK3CA and ERBB2 amplification were determined in primary tumors from 63 patients with locally advanced rectal cancer scheduled for radical treatment." (PMID 23226389, 2012). "We have retrospectively reviewed the baseline EGFR GCN, KRAS status and clinical outcome of 146 locally advanced rectal cancer (LARC) patients treated with preoperative chemoradiotherapy." (PMID 20842128, 2010). "Only a small number of studies have specifically addressed the mutational frequency of KRAS and BRAF in rectal carcinomas, reporting a mutational frequency of 21 to 46% for KRAS and about 4% for BRAF." (PMID 20979647, 2010). "Though the materials in subsets are small, women with KRAS mutant rectal cancers were diagnosed mean 10 years earlier (mean age 48, range 25-71, years) than those with KRAS wild-type rectal cancers (mean age 58, range 52-70, years)." (PMID 19832985, 2009). "Additionally, the rectal cancer exhibited proficient DNA mismatch repair (pMMR) status, ERBB2 copy number amplification, and a missense mutation, while the KRAS, NRAS, and BRAF genes were wild-type." (PMID 39985003, 2025). "KRAS p.Gly12Val (G12V) mutation, as opposed to KRAS wildtype, was associated with a significantly 53% lower likelihood of rectal cancer." (PMID 39857025, 2025). "In the context of KRAS mutant rectal cancers results have been more promising." (PMID 38623751, 2024). "These previous studies suggested the important role for KRAS status in rectal cancer." (PMID 38087207, 2023). "The KRAS-mutant rectal cancer organoids showed resistance to the EGFR inhibitor cetuximab, whereas KRAS-wild-type tumoroids displayed sensitivity to this drug, consistent with the clinical trial showing that the KRAS mutation correlates with resistance to EGFR-targeted therapy." (PMID 35551634, 2022). "Another study documented the feasibility of tumoroids in the accurate recapitulation of KRAS-mutant metastatic rectal cancer with microsatellite stability after hepatic resection and treatment with neoadjuvant combination chemotherapies of 5-FU, leucovorin, and oxaliplatin." (PMID 35551634, 2022). "Interestingly, TRPM7 expression was positively correlated with APC and KRAS gene expression in rectal cancer." (PMID 36363540, 2022). "Oncogenic KRAS is associated with poor outcomes in locally advanced rectal cancer (LARC) but the underlying biologic mechanisms are not fully understood." (PMID 33817986, 2021). "Somatic mutations in the KRAS oncogene are associated with poor outcomes in locally advanced rectal cancer but the underlying biologic mechanisms are not fully understood." (PMID 33817986, 2021). "Therefore, our data are consistent with a model where KRAS‐mt rectal cancer modulates the gene expression of surrounding fibroblasts in the microenvironment." (PMID 33817986, 2021). "Recently, we have shown no relevant heterogeneity for KRAS mutation status within and between pre- and posttherapeutic samples from the primary tumor in patients with locally advanced rectal cancer." (PMID 33002027, 2020).
rectal cancer (continued). "However, a more recent multicenter study of almost 300 patients with stage II/III rectal cancer observed pCR rates in KRAS wild-type and KRAS mutant tumors of 34 and 15%, respectively." (PMID 32923389, 2020). "We show a significant concordance of the KRAS mutation status between tumor samples obtained from the primary tumor and the corresponding metastasis and/ or local recurrence in patients with rectal cancer indicating no relevant intertumoral heterogeneity." (PMID 33002027, 2020). "Additionally, identification of somatic mutations of KRAS, NRAS, and BRAF genes were performed by direct sequencing and pyrosequencing in pretreated biopsy tissues from 57 patients diagnosed for rectal cancer." (PMID 31998419, 2020). "Nevertheless, the radiologic features of rectal cancer with KRAS mutation have not yet been fully described." (PMID 31727020, 2019). "In our case, no mutation in KRAS was detected in the primary tumor and plasma samples of rectal cancer." (PMID 31852167, 2019). "Patient 4 had a primary diagnosis of mutant RAS (KRAS G12C) metastatic rectal cancer." (PMID 30621206, 2019). "The additional texture features may provide reference information for characterizing KRAS status with the expected impact on management of individualized diagnosis and treatment of rectal cancer." (PMID 31727020, 2019). "Thus, efficient identification of KRAS status in patients with rectal cancer using non-invasively method would be of great clinical interest." (PMID 31727020, 2019). "KRAS/NRAS/BRAF mutations were not significantly related to patients' age analyzed by Student's t-test in rectal cancer." (PMID 30416987, 2018). "In a substantial proportion of patients (46%) we found a discrepancy in EGFR pathway mutations (mainly in KRAS) comparing rectal cancer tissue pre- and post-CRT, which to our knowledge has not previously been described." (PMID 28859058, 2017). "As the main result of this study in rectal cancer there seems to be no apparent heterogeneity in the KRAS mutation status." (PMID 27064574, 2016). "We aimed to assess in patients with locally advanced rectal cancer whether there is intra-specimen KRAS heterogeneity prior to and upon preoperative chemoradiotherapy (CRT), and if there are any changes in KRAS mutation status due to this intervention." (PMID 27064574, 2016). "In a systemic meta-analysis, the presence of KRAS mutation does not affect the cancer-specific survival following neoadjuvant radiotherapy with 5-FU and surgery in rectal cancer." (PMID 26252300, 2015). "The KRAS mutation status does not influence the tumor response to the radiotherapy and survival in locally advanced rectal cancer patients who received preoperative chemoradiotherapy and curative surgery." (PMID 26252300, 2015). "However, few trials have investigated the KRAS oncogene status and clinical outcome in locally advanced rectal cancer patients who received 5-FU-based neoadjuvant CRT and curative surgery." (PMID 26252300, 2015). "In this study, we aimed to determine the mutation frequencies of KRAS, BRAF and PIK3CA and to establish whether such mutations may be used as prognostic and/or predictive factors in rectal cancer patients." (PMID 23617638, 2013). "One study reported that KRAS mutation status was not related to outcomes in rectal cancer, and another study showed a contrary result." (PMID 24265711, 2013). "Of 57 rectal cancer patients in one study, 31.6% carried mutations in KRAS genes, and 9.6% had a loss of PTEN expression with no detected BRAF mutations." (PMID 24265711, 2013).
rectal cancer (continued). "Gene amplification of KRAS with or without mutation has been described in a limited number of cases, including lung, gastric, pancreatic and rectal cancers." (PMID 19545448, 2009). "Furthermore, in the subset of females with rectal cancer the KRAS mutant tumors were diagnosed mean 10 years earlier (mean age 48 years) behaviour than the wild-type tumors (mean age 58)." (PMID 19832985, 2009). "The differences in KRAS mutation rates identified suggest that sex and tumor location influence the chance of clinical usefulness of EGFR inhibitors with a particularly low likelihood of benefit among female rectal cancer patients." (PMID 19832985, 2009). "In this study, 3D V-Net architecture provided reliable rectal cancer segmentation on T2WI and DWI compared with expert-based segmentation, and auto segmentation was subjected to radiomics analysis in the prediction of KRAS/NRAS/BRAF mutation status and may produce a good prediction result." (PMID 34395262, 2021). "However, to date, there have been no studies to assess whether texture analysis of MRI can be used as an imaging biomarker for KRAS status in rectal cancer." (PMID 31727020, 2019). "This lung tropism of KRAS mutations may explain why we did not observe in our cohort a higher prevalence of rectal cancer." (PMID 27911859, 2017). "There is no information on whether this subgroup of rectal cancer patients have a different prognosis compared to patients with activating mutations nor if absence of mutation in KRAS or NRAS is predictive of response to standard radiochemotherapy." (PMID 27655166, 2016). "However, in the present rectal cancer patient with wild-type KRAS and no MSI, we discovered a novel BRAF mutation that led to a triplet deletion of the coding nucleotides 1799–1801 (TGA1799–1801 deletion; VK600–601E)." (PMID 25636897, 2015). "Most recently, Garcia-Aguilar and colleagues published their analysis of pretherapeutic biopsies from 132 patients with locally advanced rectal cancers and reported that KRAS mutations were more likely in tumors from patients without pCR, i.e., resistant tumors." (PMID 22382702, 2012). "However, KRAS mutation was still a negative predictor of survival when analysed separately for rectal cancer patients." (PMID 20959826, 2010). "KRAS leads to an epidermal-growth-factor-receptor-independent disturbance of the RAS/RAF/MAPK pathway, which regulates proliferation and survival in rectal cancer." (PMID 36986526, 2023). "This relation was observed independently of the treatment status and indicates a close interaction of mutant KRAS-activated MAPK pathway with cancer cell metabolism and oxygen demand in rectal carcinoma." (PMID 36768903, 2023). "To uncover the metabolic pathways aberrantly regulated in APC/KRAS-mutant CRC, we utilized the RNA-seq datasets from the Cancer Genome Atlas (TCGA) colon and rectal cancer (COAD-READ) cohorts." (PMID 35803966, 2022).
rectal cancer (continued). "In this study, we segmented rectal cancer via 3D V-Net on T2WI and DWI and then compared the radiomics performance in predicting KRAS/NRAS/BRAF status between DL-based auto segmentation and manual-based segmentation." (PMID 34395262, 2021). "In previous studies using the Weisenberger panel, CIMP-positive status suggested good patient outcome in KRAS wild-type or MSI CRC, but a poor prognosis in rectal cancer or CRC with chromosomal instability." (PMID 28422723, 2017). "KRAS mutations have also been associated with poorer 3‐year (79.9%) and 5‐year (56.7%) survival rates compared to KRAS‐negative patients with rectal cancer." (PMID 40653800, 2025). "It is possible that genomic instability or DNA-damage response mechanisms between colo-rectal cancer and NSCLC at baseline or in response to KRAS inhibition could explain these differences." (PMID 35267628, 2022). "Thus, we attempt to segment rectal cancer via 3D V-Net on T2WI and DWI and then compare the performance of radiomics in predicting the KRAS/NRAS/BRAF status between DL-based auto segmentation and manual-based segmentation." (PMID 34395262, 2021). "Based on RNA-seq data from a subset of our rectal cancer patient population, neither PIK3CA or KRAS mutational status, nor COX-2 mRNA expression were associated with the benefit of aspirin use or tumor downstaging." (PMID 33430037, 2021). "In our investigational study, we found that the KRAS mutation does not influence the tumor response to preoperative CRT and survival in locally advanced rectal cancer." (PMID 26252300, 2015). "No mutations were detected in BRAF exon 15 in rectal carcinomas of the test series, but one (4%) MSI-H sigmoid carcinoma with no KRAS mutation presented the mutation c.1799T > A (V600E)." (PMID 20979647, 2010). "The aims of our study were to confirm that ctDNA analysis is feasible in a population of non-metastatic rectal cancer patients, to assess KRAS/BRAF mutations as markers for ctDNA detection, and to explore potential clinical implications of detectable KRAS mutations in ctDNA." (PMID 29362371, 2018). "In our own prospective multicenter study of a 132 rectal cancer patients treated with neoadjuvant chemoradiation therapy (NCRT), we determined that KRAS mutations were more common in non-pathologic complete response (non-pCR) patients compared to patients with a pCR (49% vs. 24%, p = 0.014)." (PMID 23202889, 2012). "High phosphatidylinositol-3-kinase-mediated signaling activity of the primary tumor, rather than KRAS/BRAF mutation status, was identified as a hallmark of poor metastasis-free survival in patients with locally advanced rectal cancer undergoing radical treatment of the pelvic cavity." (PMID 23226389, 2012). "The authors found that the combination of a KRAS mutation with cyclin D1G870A (AA) and methylenetetrahydrofolate reductase (NAD[P]) C677T polymorphisms synergistically identify, with a high degree of accuracy, a subset of rectal cancer patients who do not develop a PCR in response to CRT." (PMID 23276144, 2012). "Downstream events from KRAS, such as activation of BRAF, AKT and ERK, may also confer prognostic information but have not been tested in rectal cancer (RC)." (PMID 21910869, 2011). "Dewdney analyzed 165 patients with locally advanced rectal cancer and concluded that the addition of cetuximab did not improve CR or PFS rates; however, RR and OS rates (both secondary endpoints) were significantly improved in patients with wild-type KRAS/BRAF." (PMID 29282026, 2017).